CD36 (CD36 molecule (CD36 blood group))
Diseases named in the same sentence as CD36 in open-access papers (continued):
Sharing a sentence is not in itself a finding about the gene and the disease.
atherosclerosis (continued). "In atherosclerosis, exosomes from activated platelets significantly reduce type II scavenger receptor CD36 expression in platelets, thus reducing platelet aggregation." (PMID 34513963, 2021). "In this study, we demonstrated that PP2A activity in macrophages is a crucial regulator of foam cell formation and atherosclerosis due to its ability to control the expression of scavenger receptor CD36 through the p38 MAPK signaling pathway." (PMID 35118139, 2021). "LncRNA MALAT1 can accumulate β-catenin on the CD36 promoter-binding site in macrophages, promote CD36 transcription and lipid uptake 114, and ultimately accelerate the occurrence of atherosclerosis." (PMID 34803512, 2021). "It has also been demonstrated that CD36 contributes to thrombus formation in response to vascular injury in mice confirming the role of this pathway in platelet activation and promoting atherosclerosis." (PMID 34535958, 2021). "For example, CD36 is reportedly present during the initiation and progression of atherosclerosis by internalizing LDL and forming lipid-filled macrophage foam cells." (PMID 33498620, 2021). "In an in vivo study, dietary intake of walnut showed a protective effect on atherosclerosis with a decrease in CD36 expression in apoE‐/‐ mice." (PMID 34136191, 2021). "Despite the high degree of homology, CD36 and SR-B1 have been reported to be distinctly different in their roles in lipid metabolism and atherosclerosis wherein, CD36 plays a major role in contributing to 60–70% uptake and clearance of modified LDL45." (PMID 33441791, 2021). "In this report, we show evidence to support the important role of EC CD36 in regulating systemic metabolism and in the development of atherosclerosis." (PMID 34888367, 2021). "CD36, initially characterized as a scavenger receptor at the platelet membrane that takes up lipoproteins, is involved in the pathogenesis of atherosclerosis." (PMID 33921168, 2021). "Both scavenger receptors, CD5L and CD36, are essential molecules related to inflammatory responses and atherosclerosis mediated by macrophages; while CD36 oxLDL endocytosis prompts foam cell formation, CD5L facilitates CD36-mediated oxLDL uptake." (PMID 34629330, 2021). "Taken together, these data support a significant role for EC CD36 in systemic metabolism and reveal sex-specific impact on atherosclerosis and energy substrate use." (PMID 34888367, 2021). "CD36 is involved in fatty acid uptake and metabolism, inflammation cascade, angiogenesis, apoptosis, thrombosis, atherosclerosis, Alzheimer’s disease, and insulin resistance." (PMID 34283828, 2021). "These preliminary results depict that pMSCs not only inhibit agonist‐induced platelet activation but DBMSCs also inhibit ox‐LDL‐induced‐CD36‐mediated platelet aggregation providing a direct link between pMSCs therapy, hyperlipidaemia and atherosclerosis." (PMID 34535958, 2021). "A recent APO-E-null mouse model of atherosclerosis found that simvastatin administration reduced CD36 expression as well as atherosclerosis and inflammatory signalling compared with controls." (PMID 33182772, 2020). "It has been reported that CD36 is a trigger for the inflammation response and influences the development of foam cells to activate atherosclerosis." (PMID 32855961, 2020). "The fatty acid transporter CD36 is believed to play a role in the development of atherosclerosis through its ability to bind and internalize modified lipids, such as ox-LDL." (PMID 32498389, 2020). "SR-A1 and CD36 play crucial roles in lipid accumulation and the initiation and development of atherosclerosis." (PMID 33261070, 2020). "Under diabetic conditions, foam cell formation and the related CD36 gene expression of macrophages have been known to be enhanced, contributing to the accelerated atherosclerosis in diabetes mellitus." (PMID 33291667, 2020).
atherosclerosis (continued). "CD36 is involved in macrophage foam cell formation and atherosclerosis progression by mediating endocytosis and conversion of oxLDL into cholesterol crystals, thus promoting complement and NLRP3 inflammasome activation." (PMID 33117348, 2020). "On the other hand, expression of SR-A and CD36 enhanced by high glucose is known to be one mechanism for an increased rate of atherosclerosis in diabetes." (PMID 32640667, 2020). "In macrophages, the fatty acid transporter CD36 promotes atherosclerosis through the uptake of oxidized low-density lipoprotein (ox-LDL) and subsequent foam cell development, and the release of inflammatory mediators." (PMID 32498389, 2020). "On macrophages, CD36 is known to contribute to atherosclerosis progression via modified oxLDL phagocytosis and the formation of foam cells." (PMID 33326419, 2020). "In summary, our results suggested that the inhibition of USP14 decreases foam cell formation by down‐regulating CD36‐mediated lipid uptake and provides a potential therapeutic target for atherosclerosis." (PMID 31970862, 2020). "Previous studies demonstrated the involvement of CD36 in the progression of atherosclerosis, and also that deletion or blockage of the CD36-induced signalling pathway decreased the development of atherosclerotic lesions in mice." (PMID 32498389, 2020). "In conclusion, USP10 promotes the development and progression of atherosclerosis through stabilizing CD36 protein expression." (PMID 33197885, 2020). "Our findings revealed a decisive role for the CD36 scavenger in vascular calcification under hyperglycemic conditions and indicated potential mechanistic insights into the acceleration of atherosclerosis in diabetic subjects." (PMID 33028031, 2020). "Ligand engagement by CD36 has important implications in cardiovascular biology, including events leading to atherosclerosis, angiogenesis, diabetic retinopathy and age-related macular degeneration (AMD)." (PMID 32717955, 2020). "CD36 is a membrane glycoprotein that belongs to the class B scavenger receptor family, and is known to be involved in lipid metabolism as well as atherosclerosis development." (PMID 33008402, 2020). "It is believed that CD36 polymorphisms confer susceptibility for hypertension and/or CAD due to the roles of CD36 in the regulation of lipid metabolism, atherosclerosis, and blood pressure." (PMID 31185924, 2019). "The scavenger receptor CD36 recognizes oxLDL and mediates its uptake into cells and plays a key role in atherosclerosis pathogenesis." (PMID 31772703, 2019). "The interaction of ox-LDL and CD36 also induces cytokine release and immune-cell infiltration, which accelerate the process of atherosclerosis." (PMID 31410189, 2019). "EP80317 is an hexapeptide that serves as a ligand for CD36 and features protective effects under conditions such as atherosclerosis and vascular inflammation." (PMID 30886580, 2019). "Further, IFNγ-activated macrophages significantly upregulate the expression CD36 in disease models of atherosclerosis." (PMID 31312197, 2019). "In conclusion, our results show that myricetin regulates cholesterol uptake in macrophages through CD-36 pathway, resulting in an attenuation of atherosclerosis lesions." (PMID 31049071, 2019). "Though the CD36 signaling pathway in atherosclerosis is potentially important, the downstream signaling pathway in endothelial cells is not fully understood." (PMID 31772703, 2019). "Studies using apolipoprotein (apo) E-null mice as a model of fatty streak lesions and atherosclerosis have shown that CD36 was essential in that process." (PMID 29883404, 2018). "Vim−/− mice displayed decreased atherogenesis despite increased vascular inflammation and increased CD36 expression on macrophages in two mouse models of atherosclerosis." (PMID 30451917, 2018).
atherosclerosis (continued). "This study was conducted to investigate the potential association of circulating CD36+ and BLTR1+ MMVs with femoral atherosclerosis on the one hand, and AA and EPA contents in atherosclerotic plaques, plasma, and granulocytes on the other." (PMID 30425991, 2018). "Scavenger receptors such as scavenger receptors class A (SR-A), scavenger receptor class B (CD36), and lectin-type oxidized LDL receptor (LOX-1) have been implicated in the pathogenesis of atherosclerosis." (PMID 30498447, 2018). "Specifically, CD36 and SR-A are principal SRs accounting for up to 90% of oxLDL loading in macrophages, which are key players in all stages of atherosclerosis." (PMID 30038821, 2018). "One of the best characterized functions of CD36 is the uptake of oxLDL by macrophages to form foam cells, a key event in the initiation and progression of atherosclerosis." (PMID 30544997, 2018). "BLTR1+ MVs and CD14+CD36+ MVs has potential as markers of atherosclerosis pathophysiology, but this needs further investigation." (PMID 30425991, 2018). "Functionally, MT4-MMP-null Mafb+AIM+ peritoneal macrophages express higher AIM and scavenger receptor CD36, are more resistant to apoptosis, and bind acLDL avidly, all of which contribute to atherosclerosis." (PMID 29500407, 2018). "CD36 is a key element in the relationship between atherosclerosis and glucose metabolism, as it has multiple ligands and it is present in some tissues where this receptor acts as mediator in this process." (PMID 28729885, 2017). "In our study, we demonstrated that the role of macrophagic CD146 in atherosclerosis is mainly through promotion of CD36-dependent formation of foam cells and their retention in the plaques." (PMID 28084332, 2017). "CD36 is also expressed on macrophages as a receptor for oxidized low-density lipoproteins and plays an important role in the development of atherosclerosis." (PMID 28804718, 2017). "We have recently shown that nicotine promotes foam cell formation and atherosclerosis via upregulating macrophage CD36 signaling." (PMID 29236702, 2017). "Overall, our data demonstrate that lanatoside C aggravates the development of atherosclerosis by inducing PPARβ/δ expression, which mediates upregulation of SR-A and CD36, and promotes oxLDL uptake and foam-cell formation." (PMID 26821916, 2016). "OxLDL can promote atherosclerosis development by inducing the recruitment of platelet-activating factor receptor and CD36 in detergent resistant membranes." (PMID 26628893, 2015). "Accordingly, knockout of CD36 in proatherogenic ApoE-null mice protects the development of atherosclerosis lesions in these animals." (PMID 26557864, 2015). "Murine atherosclerosis model, crossing the CD36-null mouse into an apolipoprotein E-null atherogenic strain developed significantly less atherosclerosis." (PMID 26633327, 2015). "The most convincing data supporting a critical role of CD36 in foam cell formation and atherosclerosis are from studies of a CD36-null engineered mouse model." (PMID 26557864, 2015). "Ox-LDL acts by binding to several SRs, including SR-A, SR-BI, CD36, and lectin-like oxidized low-density lipoprotein receptor-1 (LOX-1) and transforms macrophages to foam cells, which are a hallmark of atherosclerosis." (PMID 26697490, 2015). "CD36 has been shown to play a role in inflammasome activation in AD, atherosclerosis and type 2 diabetes." (PMID 24625061, 2014). "Nonetheless, like SR-AI, the precise role of CD36 in the development of atherosclerosis in vivo is still inconclusive." (PMID 24466325, 2014). "Type B scavenger receptors (SR), like CD36, are molecules possibly involved in the pathogenesis of atherosclerosis." (PMID 25006585, 2014). "RA patients with subclinical atherosclerosis showed low membrane expression of CD36 in PBMC and increased serum proinflammatory cytokines." (PMID 25006585, 2014). "We found low CD36 membrane expression in PBMC from RA patients with subclinical atherosclerosis (P < 0.001)." (PMID 25006585, 2014).
atherosclerosis (continued). "While Griffin demonstrated that high glucose-induced increased translation of CD36 in macrophage promotes atherosclerosis." (PMID 25048611, 2014). "Unfortunately, the in vivo implication and the role of Nef-mediated CD36 downregulation in determining or contributing to the onset of atherosclerosis and CVD are difficult to establish by the ART in HIV-infected patients." (PMID 24705461, 2014). "In this study, we showed that RA patients with subclinical atherosclerosis showed low membrane expression of CD36 in PBMC and increased serum proinflammatory cytokines." (PMID 25006585, 2014). "TNFα promotes atherosclerosis through the inhibition of cholesterol efflux, favoring the cholesterol uptake by CD36 and other SR via protein kinase pathway." (PMID 25006585, 2014). "CD36 is best characterized as a free fatty acid transporter involved in different biological processes like angiogenesis, inflammation, lipid metabolism, atherosclerosis and platelet activation." (PMID 24766787, 2014). "Rcan1 regulates CD36 expression and its genetic inactivation reduced atherosclerosis extension and severity in Apoe−/− mice." (PMID 24127415, 2013). "CD36 has been proposed as a biomarker of macrophage activation and inflammation and atherosclerosis." (PMID 24282409, 2013). "Macrophage CD36 is believed to play a critical role in the initiation and progression of atherosclerosis through its ability to bind and internalize LDL, thereby facilitating in the formation of foam cells." (PMID 24069322, 2013). "The scavenger protein CD36 has been shown to play a substantial role in the pathogenesis of atherosclerosis, largely through its interaction with oxidised LDL." (PMID 24069322, 2013). "CD36, a class B scavenger receptor, participates in the pathogenesis of metabolic dysregulation such as insulin resistance, hepatic steatosis, and atherosclerosis." (PMID 24016701, 2013). "The increased movement of L. major-activated leukocytes to the site of atherosclerosis is suggested by the higher inflammatory infiltration and the higher expression of CD36, the major macrophage scavenger receptor for abnormal (oxidized) LDL." (PMID 23710353, 2013). "Correlation between the anti-CD36 activity of these inhibitors and the known pathophysiological activity of this scavenger receptor in the development of atherosclerosis and diabetes were observed at pharmacological doses." (PMID 22662181, 2012). "The first CD36 in vivo activity to be examined was its implication in the development of atherosclerosis using a well characterized animal model." (PMID 22662181, 2012). "CD36 also influences various diseases, including angiogenesis, thrombosis, atherosclerosis, malaria, diabetes, steatosis, dementia and obesity." (PMID 24970143, 2012). "Macrophage CD36 plays a very important role in the physiological process including apoptotic cell clearance and pathogenesis, of many diseases such as atherosclerosis, Alzheimer's disease and Plasmodium falciparum malaria infection." (PMID 22287954, 2012). "As a widely expressed receptor with multiple ligands, CD36 is involved in a numerous biological and pathological processes including fatty acid uptake and sensing, innate immunity, inflammation, atherosclerosis, and angiogenesis." (PMID 22216174, 2011). "JNK activation is a critical step in foam cell formation and atherogenesis, as inhibition or deletion of JNK has been shown by our group to block CD36-mediated oxLDL uptake and by others to inhibit atherosclerosis in an apoe null mouse model." (PMID 22216174, 2011). "It has been shown as in vivo that hypercholesterolemia increases foam cell formation and atherosclerosis by increasing CD36 mRNA expression and PKC activity in rabbits." (PMID 22043207, 2010). "The presence of foam cells in the atherosclerosis process confirms the importance of CD36 scavenger receptors." (PMID 22043207, 2010).
atherosclerosis (continued). "Cluster of differentiation 36 (CD36) is a transmembrane glycoprotein involved in many biological processes, such as platelet biology, angiogenesis and in the aetiopathology of atherosclerosis and cardiovascular diseases." (PMID 19847289, 2009). "Studies employing transgenic and knock-out mice have demonstrated that CD36 is proatherogenic according to observations that targeted disruption of the gene was protective against atherosclerosis." (PMID 18302760, 2008). "The phagocytosis of oxidized low density lipoproteins (LDLs) accumulated in the subendothelium by mononuclear cells influences atherosclerosis and depends on CD36 expression." (PMID 17335569, 2007). "Additionally, we showed that mtROS levels are persistently elevated in circulating monocytes and aortic macrophages in a CD36-dependent manner, contributing to the initiation of atherosclerosis." (PMID 40250804, 2025). "Elevated sCD36 levels may reflect atherosclerosis progression in diabetes, indicating the need for further studies to clarify CD36’s role in cardiometabolic dysfunction." (PMID 40867895, 2025). "Consistently, immunofluorescence staining confirmed elevated CD36 expression in aortic plaques from ApoE−/−EP4MKO mice compared to ApoE−/−EP4Flox mice, suggesting EP4 deficiency exacerbates atherosclerosis through CD36-mediated inflammatory and metabolic dysregulation." (PMID 40643540, 2025). "Among the pattern recognition receptors (PRRs) involved in macrophage recognition of oxLDL, CD36 plays a critical role in the onset and development of chronic inflammatory pathologies, such as atherosclerosis and degenerative retinal diseases, namely, age-related macular degeneration." (PMID 40072113, 2025). "Therefore, CD36 represents a viable target for the molecular imaging of atherosclerosis, particularly vulnerable plaque." (PMID 40284439, 2025). "With the assistance of the class A scavenger receptors (SR-A) and CD-36, monocytes could absorb oxidized low-density lipoprotein and differentiate into foam cells, which has played a crucial role in the initial stage of atherosclerosis formation." (PMID 40295953, 2025). "Furthermore, fraxin downregulated IL-6 and TNF-α expression and lowered the gene and protein levels of FAT/CD36, controlling key targets in signaling pathways related to lipid metabolism and atherosclerosis." (PMID 41458968, 2025). "Playing a critical role in the early manifestation of atherosclerosis, the cluster of differentiation 36 receptor (CD36) binds and facilitates oxLDL uptake by macrophages through the formation of a heteromeric complex consisting of tetraspanin CD9, integrins β1/2 and the adaptor receptor FcRγ." (PMID 40072113, 2025). "Furthermore, inhibiting the interaction between CD36 and its downstream molecule, TNF receptor-associated factor 6 (TRAF6) almost completely halted the progression of atherosclerosis." (PMID 40284439, 2025). "CD36 undergoes ubiquitination and covalent attachment of both K48 and K63 polyubiquitin chains; CD36-ubiquitin cleavage by deubiquitinases such as UCHL1 or USP11 modulates foam cell formation and atherosclerosis-linked outcomes." (PMID 40563926, 2025). "Knockout of the scavenger receptors Cd36 and Msr1 resulted in reduced lipid uptake and lower intracellular lipid content in macrophages, as well as a relative suppression of macrophage proliferation in both established and early atherosclerosis." (PMID 40956333, 2025). "Furthermore, lipid metabolism disorders appear early in atherosclerosis, with CD36 expression positively correlated with lipid dysregulation, increasing as the disease progresses." (PMID 40284439, 2025).